RNU4-4P (RNA, U4 small nuclear 4, pseudogene)
Synonyms: U4; U4/5; formerly RNU4P4
Gene: Small nuclear RNA gene on chromosome 3 (172,796,429 to 172,796,558, reverse strand). Ensembl gene ENSG00000201458.
Homologues: Orthologues: chimpanzee U4 (98% identical), dog U4 (62% identical), guinea pig U4 (58% identical), tropical clawed frog U4 (57% identical), tropical clawed frog U4 (55% identical), tropical clawed frog U4 (52% identical), tropical clawed frog U4 (50% identical). Paralogues in human: U4 (65% identical), RNU4-82P (62% identical), RNU4-26P (61% identical), RNU4-59P (61% identical), RNU4-91P (61% identical), RNU4-34P (59% identical), RNU4-49P (59% identical), RNU4-53P (59% identical), RNU4-55P (59% identical), RNU4-81P (59% identical), RNU4-72P (58% identical), RNU4-89P (58% identical), and 79 more.